SAPCD2 (suppressor APC domain containing 2)
Description:
Plays a role in planar mitotic spindle orientation in retinal progenitor cells (RPCs) and promotes the production of symmetric terminal divisions (By similarity). Negatively regulates the mitotic apical cortex localization of GPSM2. Involved also in positive regulation of cell proliferation and tumor cell growth.
Synonyms: C9orf140; p42.3
Tractability: Antibody: UniProt places it where antibodies can reach, with medium confidence; its Gene Ontology location is reachable by antibodies, with medium confidence.
Gene: Protein-coding gene on chromosome 9 (137,062,127 to 137,070,593, reverse strand). Ensembl gene ENSG00000186193.
Subcellular location: Cytoplasm; Nucleus; Cytoplasm, cell cortex; Apical cell membrane; Cell junction, tight junction
Subcellular location (Human Protein Atlas): Cytosol; Nucleoli; Nucleoplasm
Gene Ontology:
Molecular function: protein binding
Biological process: negative regulation of protein localization to cell cortex; positive regulation of cell population proliferation; establishment of mitotic spindle orientation; regulation of establishment of planar polarity; symmetric cell division
Cellular component: apical cortex; apical junction complex; cytoplasm; cytosol; nucleolus; nucleoplasm; nucleus; apical plasma membrane; bicellular tight junction; cell cortex
Genetic constraint (gnomAD): Loss-of-function variants: 34 observed, 22.88 expected, observed/expected ratio (o/e) 1.49, 90% interval 1.12 to 1.88. The synonymous counts are far from expectation, so gnomAD's model fits this gene poorly and the ratio says little. Missense variants: 543 observed, 383.43 expected, observed/expected ratio (o/e) 1.42, 90% interval 1.32 to 1.52. Synonymous variants: 258 observed, 172.12 expected, observed/expected ratio (o/e) 1.5, 90% interval 1.35 to 1.66.
Homologues: Orthologues: chimpanzee SAPCD2 (99% identical), macaque SAPCD2 (97% identical), dog SAPCD2 (85% identical), pig SAPCD2 (84% identical), rat Sapcd2 (79% identical), guinea pig SAPCD2 (75% identical), mouse Sapcd2 (75% identical), rabbit SAPCD2 (73% identical), tropical clawed frog SAPCD2 (29% identical). Paralogues in human: SAPCD1 (13% identical).
Diseases named in the same sentence as SAPCD2 in open-access papers:
SAPCD2 is named in the same sentence as 37 diseases in open-access papers, as found by Europe PMC text mining. Sharing a sentence is not in itself a finding about the gene and the disease. The quoted sentences say what the papers report.
gastric cancer (12 papers, 2011 to 2022). A primary or metastatic malignant neoplasm involving the stomach. "SAPCD2 may be associated with gastric cancer cell proliferation." (PMID 34540835, 2021). "Silencing SAPCD2 significantly inhibits cancer cell proliferation and colony formation of gastric cancer cells." (PMID 34540835, 2021). "SAPCD2 has been reported to be upregulated in various kinds of tumors, including breast cancer, gastric cancer, hepatocellular carcinoma, colorectal carcinoma, glioblastoma, nasopharyngeal carcinoma, lung adenocarcinoma, melanoma, and renal cell cancer." (PMID 33384953, 2020). "In addition to its function as an oncogene in gastric cancer, SAPCD2 has also been identified as a potential oncogene in several other cancer types." (PMID 35517423, 2022). "Bioinformatics analysis in gastric cancer predicted a role of SAPCD2 in a signaling network also comprising S100A11, RAGE, P38, MAPK, microtubule-associated protein, spindle protein, and centromere protein, regulating cell proliferation, or in the Ras-Raf-1-MEK-MAPKK-MAPK pathway." (PMID 32055236, 2020). "Although SAPCD2 is revealed to function as an oncogene in melanoma, gastric cancer, HCC, and colorectal cancer, the biological roles of SAPCD2 in NPC are still unknown." (PMID 31173488, 2019). "Suppressor anaphase-promoting complex domain containing 2 (SAPCD2), also known as p42.3 or C9orf140, is a cell cycle-dependent gene which was first identified in the gastric cancer (GC) cell line, BGC823." (PMID 32055236, 2020). "Since it was first identified in gastric cancer, suppressor anaphase-promoting complex domain containing 2 (SAPCD2), also referred to as C9orf140 or p42.3, has been shown to play an important role in controlling spindle orientation and divisions as a cell cycle-dependent factor." (PMID 33384953, 2020).
nasopharyngeal carcinoma (7 papers, 2019 to 2023). A carcinoma arising from the nasopharyngeal epithelium. "The mRNA and protein level of SAPCD2 was found to be upregulated in nasopharyngeal carcinoma tissues, and gain-of-function and loss-of-function experiments demonstrated that SAPCD2 could promote nasopharyngeal carcinoma cell proliferation, migration, and invasion." (PMID 35071775, 2022). "PXN‐AS1‐L thus promotes the malignancy of nasopharyngeal carcinoma cells via upregulation of SAPCD2." (PMID 35562740, 2022). "A recent study by Jia and colleagues have reported that the PXN-AS1-L-induced increased expression of SAPCD2 by disrupting the binding of the microRNAs-mediated silencing complex to SAPCD2 predicted a worse prognosis in nasopharyngeal carcinoma patients." (PMID 33384953, 2020). "In addition, lncRNA PXN-AS1-L increases the stability and expression of SAPCD2 mRNA through binding to the 3′ UTR; increased SAPCD2 promotes the malignancy of nasopharyngeal carcinoma." (PMID 32716908, 2020).
breast carcinoma (6 papers, 2014 to 2022). "In the investigation of the mechanisms of action of SAPCD2, it was found that SAPCD2 promotes the progression of breast cancer by stimulating expression of Yes-associated protein (YAP), an oncoprotein serving as a transcriptional co-activator with TAZ in YAP/TAZ signaling." (PMID 35517423, 2022). "They further show that depletion of SAPCD2 expression levels in vitro decreased breast cancer cell viability, migration, and invasion." (PMID 35517423, 2022). "A more recent study revealed the role of SAPCD2 in breast cancer." (PMID 35517423, 2022). "Importantly, breast cancer patients with high SAPCD2 expression had poorer overall survival rates than those with low SAPCD2 expression." (PMID 33384953, 2020). "Moreover, SAPCD2 expression was reported to be significantly upregulated in breast cancer tissues, and its expression was further increased with advanced tumor stage." (PMID 33384953, 2020). "Collectively, our findings in combination with existing reports indicate that the activation of the Hippo signaling pathway plays an important role in mediating the functional role of SAPCD2 in tumor growth and metastasis, at least in the context of of fibrosarcoma and breast cancer." (PMID 33384953, 2020). "Oncogenic genes like FAM83D, CTDSP1, and SAPCD2 were downregulated in all three cells, and tumor suppressor genes (TSGs) like ZNF292, ANKRD12, NKAPL, and CCL21 were upregulated in all three breast cancer cells upon curcumin treatment." (PMID 34981672, 2022). "For example, SAPCD2 enhances breast cancer cell proliferation ability by modulating the expression of YAP/TAZ, thereby promoting the progression of breast cancer." (PMID 34540835, 2021).
melanoma (4 papers, 2019 to 2022). A malignant, usually aggressive tumor composed of atypical, neoplastic melanocytes. "An interesting finding in melanoma reveals that a DNA vaccine targeting the SAPCD2 gene demonstrated a potential therapeutic effect on melanoma progression in a melanoma mouse model." (PMID 35517423, 2022). "Besides using siRNA to target SAPCD2, a DNA vaccine targeting the SAPCD2 gene has been explored and exhibited therapeutic activity on melanoma progression in a melanoma mouse model." (PMID 35517423, 2022). "A role of SAPCD2 in the promotion of tumor metastasis and EMT progression through Wnt, MAPK, and PI3K/AKT has been proposed in melanoma and renal cell cancer." (PMID 32055236, 2020).
colorectal cancer (3 papers, 2019 to 2020). A primary or metastatic malignant neoplasm that affects the colon or rectum. "Further studies should be conducted on the related signaling pathway with SAPCD2 in the progression of colorectal cancer." (PMID 32055236, 2020). "To date, little is known about the function of SAPCD2 in colorectal carcinoma (CRC)." (PMID 32055236, 2020).
hepatocellular carcinoma (3 papers, 2020 to 2022). A malignant tumor that arises from hepatocytes. "SAPCD2 has also been identified as a potential driving factor in the tumorigenicity of hepatocellular carcinoma (HCC)." (PMID 35517423, 2022).
adenoma (2 papers, 2020 to 2021). A neoplasm arising from the epithelium. "Previous studies have shown that SAPCD2 expression was significantly higher in colon cancer tissues than in adenoma and normal epithelial tissues, and it significantly promoted cell proliferation, migration, and invasion both in vitro and in vivo." (PMID 33670062, 2021). "We found that SAPCD2 expression substantially differed in normal epithelium compared to adenoma and CRC tissues." (PMID 32055236, 2020). "IHC showed that SAPCD2 expression was significantly higher in CRC tissues compared to adenoma and normal epithelium tissues and was correlated with tumor location (p = 0.018)." (PMID 32055236, 2020). "Moreover, the expression of SAPCD2 among the normal epithelium tissues, adenoma tissues and CRC tissues was obviously different (p < 0.001)." (PMID 32055236, 2020). "In sum, our findings demonstrated that the expression of SAPCD2 is higher in CRC tissues than in normal epithelium and is involved in the “normal epithelium-adenoma–CRC” transition." (PMID 32055236, 2020). "IHC staining was performed to analyze the expression of SAPCD2 in CRC, adenoma, and normal epithelium tissues from 410 CRC and 50 adenoma patients." (PMID 32055236, 2020). "Immunohistochemistry (IHC) for SAPCD2 was performed in 410 pairs of CRC specimens and corresponding normal epithelial tissues, and in 50 adenoma tissues." (PMID 32055236, 2020).
fibrosarcoma (2 papers, 2020 to 2022). A malignant mesenchymal fibroblastic neoplasm affecting the soft tissue and bone. "A better understanding of the underlying mechanism and the functional role of SAPCD2 in the pathogenesis of lung metastatic fibrosarcoma will facilitate the development of an anti-metastatic therapeutic strategy for the treatment of fibrosarcoma." (PMID 33384953, 2020). "Loss-of-function assays showed that silencing SAPCD2 not only attenuated the proliferation and promoted the apoptosis of fibrosarcoma cells in vitro, but also inhibited the lung metastasis of fibrosarcoma cells in vivo." (PMID 33384953, 2020). "Loss-of-function experiments showed that silencing SAPCD2 inhibited the proliferation and increased the apoptosis of fibrosarcoma cells in vitro, and repressed the lung metastasis of fibrosarcoma cells in vivo." (PMID 33384953, 2020). "In the current study, our results demonstrated that overexpression of SAPCD2 was observed in fibrosarcoma tissues, and was associated with early progression and metastasis, and poor prognosis in fibrosarcoma patients." (PMID 33384953, 2020). "Kaplan-Meier analysis revealed that fibrosarcoma patients exhibiting a higher expression level of SAPCD2 are correlated with worse overall survival." (PMID 35517423, 2022). "Kaplan-Meier survival analysis further showed that fibrosarcoma patients with high SAPCD2 expression had poorer overall survival than those with low SAPCD2 expression." (PMID 33384953, 2020). "Taken together, these findings indicated that silencing SAPCD2 activates the Hippo signaling pathway in fibrosarcoma cells." (PMID 33384953, 2020). "In the current study, our results demonstrated that SAPCD2 was upregulated in fibrosarcoma tissues and cell lines, and SAPCD2 overexpression predicted early progression and metastasis, and poor prognosis in fibrosarcoma patients." (PMID 33384953, 2020). "Our results further showed that silencing SAPCD2 inhibited the proliferation and increased the apoptosis of fibrosarcoma cells in vitro." (PMID 33384953, 2020). "Collectively, these results indicated that silencing SAPCD2 inhibits proliferation and promotes apoptosis by activating the Hippo signaling pathway in fibrosarcoma cells." (PMID 33384953, 2020). "Here, we reported that SAPCD2 expression was markedly elevated in fibrosarcoma tissues, and its expression was differentially upregulated in fibrosarcoma cell lines compared with that in several primary fibroblast cell lines." (PMID 33384953, 2020). "The primary findings of the current study shed light on the critical role of SAPCD2 in the lung metastasis of fibrosarcoma." (PMID 33384953, 2020). "Kaplan-Meier survival analysis revealed that SAPCD2 overexpression was significantly correlated with early progression and metastasis, and poor prognosis in fibrosarcoma patients." (PMID 33384953, 2020). "Statistical analysis revealed that overexpression of SAPCD2 was significantly and positively correlated with metastatic status in fibrosarcoma patients (P = 0.028)." (PMID 33384953, 2020). "Mechanistic investigation further demonstrated that silencing SAPCD2 inhibited the proliferation and lung metastasis of fibrosarcoma cells by activating the Hippo signaling pathway." (PMID 33384953, 2020). "Silencing SAPCD2 inhibited the proliferation and increased the apoptosis of fibrosarcoma cells in vitro, and repressed the lung metastasis of fibrosarcoma cells in vivo." (PMID 33384953, 2020). "In summary, our findings demonstrated that SAPCD2 functions as an oncogenic regulator to promote the proliferation and lung metastasis of fibrosarcoma cells by inactivating the Hippo signaling pathway." (PMID 33384953, 2020). "The basic information of 59 patients with fibrosarcoma for SAPCD2 immunohistochemical staining analysis." (PMID 33384953, 2020). "The relationship between SAPCD2 protein level and clinical pathological characteristics in 59 patients with fibrosarcoma." (PMID 33384953, 2020).
fibrosarcoma (continued). "In conclusion, SAPCD2 promotes the proliferation and lung metastasis of fibrosarcoma cells by regulating the activity of Hippo signaling, and this mechanism represents a potential therapeutic target for the treatment of lung metastatic fibrosarcoma." (PMID 33384953, 2020). "Our results further revealed that silencing SAPCD2 inhibited the proliferation and lung metastasis of fibrosarcoma cells by activating the Hippo signaling pathway." (PMID 33384953, 2020). "Therefore, our results revealed that silencing SAPCD2 inhibits the proliferation and promotes the apoptosis of fibrosarcoma cells in vitro." (PMID 33384953, 2020). "Consistently, our results were further supported by the findings from the fibrosarcoma datasets from TCGA that fibrosarcoma patients with high SAPCD2 expression exhibited poor overall survival and early progression-free survival compared with those with low SAPCD2 expression." (PMID 33384953, 2020). "Therefore, our results reveal a novel mechanism by which SAPCD2 promotes the proliferation and lung metastasis of fibrosarcoma cells." (PMID 33384953, 2020). "Based on the SI of the 66 fibrosarcoma samples examined above by IHC, low and high SAPCD2 expression was stratified by the following criteria: SI ≤ 3 was used to define fibrosarcoma tissues with low SAPCD2 expression, and SI ≥ 4 was used to define fibrosarcomatissues with high SAPCD2 expression." (PMID 33384953, 2020). "Taken together, our findings suggest that SAPCD2 may have favorable prospects as a potential prognostic marker in fibrosarcoma." (PMID 33384953, 2020). "In the current study, our results showed that SAPCD2 expression was elevated in clinical fibrosarcoma tissues and was significantly correlated with early progression, distant metastasis, and poor overall survival in fibrosarcoma patients." (PMID 33384953, 2020). "However, the clinical significance and biological function of SAPCD2 in fibrosarcoma remain poorly known." (PMID 33384953, 2020). "The clinical significance of SAPCD2 in fibrosarcoma was further investigated." (PMID 33384953, 2020). "Therefore, our results indicated that overexpression of SAPCD2 is significantly correlated with early progression and metastasis, and poor overall prognosis in fibrosarcoma patients." (PMID 33384953, 2020). "Therefore, our findings in the current study reveal a novel mechanism by which SAPCD2 promotes the lung metastasis of fibrosarcoma, and identify a critical role of SAPCD2 in the lung metastasis of fibrosarcoma." (PMID 33384953, 2020). "Importantly, our results further demonstrated that silencing SAPCD2 inhibited the lung metastasis of fibrosarcoma cells in lung colonization models in vivo." (PMID 33384953, 2020). "In this study, our results showed that SAPCD2 is dramatically upregulated in clinical fibrosarcoma tissues, and this upregulation is significantly correlated with early progression and metastasis, and poor overall prognosis in fibrosarcoma patients." (PMID 33384953, 2020). "Therefore, our results determine an oncogenic role of SAPCD2 in the lung metastasis of fibrosarcoma." (PMID 33384953, 2020). "However, little is known about the clinical significance and functional role of SAPCD2 in fibrosarcoma, especially metastatic fibrosarcoma." (PMID 33384953, 2020). "Furthermore, compared with downexpression of SAPCD2, overexpression of SAPCD2 predicted shortened progression-free and distant metastasis-free survival in fibrosarcoma patients." (PMID 33384953, 2020). "In subcutaneous xenografts, silencing SAPCD2 dramatically attenuated the primary growth and tumorigenic abilities of fibrosarcoma cells in vivo, as demonstrated by the reduced tumor volume and tumor weight in the mice inoculated with SAPCD2-silenced fibrosarcoma cells." (PMID 33384953, 2020). "Importantly, silencing SAPCD2 repressed lung metastasis of fibrosarcoma cells in vivo." (PMID 33384953, 2020).
fibrosarcoma (continued). "However, the clinical significance of SAPCD2 in the progression and metastasis of fibrosarcoma is largely unknown." (PMID 33384953, 2020). "The expression of SAPCD2 was highly correlated with the signatures of Hippo signaling, supporting the notion that Hippo signaling may mediate the inhibitory effect of silencing SAPCD2 on the lung colonization and cell proliferation of fibrosarcoma cells." (PMID 33384953, 2020). "Real-time PCR analysis showed that silencing SAPCD2 decreased expression levels of multiple downstream genes of the Hippo pathway, including CTGF, CYR61, SOX9, HOXA1, RPL13A, and PPIA in fibrosarcoma cells." (PMID 33384953, 2020). "However, the clinical significance and biological roles of SAPCD2 in fibrosarcoma remain unknown." (PMID 33384953, 2020). "Experimental investigations revealed that silencing SAPCD2 expression inhibits proliferation and induces apoptosis in human fibrosarcoma cell lines HT-1080 and SW684 and reduces lung metastasis in vivo in a murine subcutaneous fibrosarcoma xenograft model." (PMID 35517423, 2022). "Luciferase reporter analysis showed that silencing SAPCD2 reduced the luciferase reporter activity of HOP-Flash, but not that of HIP-Flash, suggesting that silencing SAPCD2 inhibited TEAD-dependent luciferase activity in fibrosarcoma cells." (PMID 33384953, 2020). "First, the expression of SAPCD2 in hDFPCs, human lung fibroblast primary cells (hLFPCs), human mammary fibroblast primary cells (hMFPCs), human embryonic lung fibroblasts (HFL1), and two fibrosarcoma cell lines, HT-1080 and SW 684, was examined by real-time PCR and western blot." (PMID 33384953, 2020).
neuroblastoma (2 papers, 2022 to 2024). Neuroblastoma (NB) is the most common solid, extracranial childhood tumor. "However, the functions and underlying mechanisms of SAPCD2 in the progression of neuroblastoma (NB) remain elusive." (PMID 35197448, 2022). "By directly binding to and altering the subcellular distribution of cytoplasmic E2F7, suppressor anaphase-promoting complex domain 2 (SAPCD2) promotes neuroblastoma progression by modulating E2F activity and affecting genes involved in the cell cycle and chromosomal instability." (PMID 38992083, 2024).